CXCL9 (C-X-C motif chemokine ligand 9)
Diseases named in the same sentence as CXCL9 in open-access papers (continued):
Sharing a sentence is not in itself a finding about the gene and the disease.
tumor (continued). "Instead, engineered T cells + CD40 agonist, which we previously showed to promote the persistence of engineered T cells in autochthonous PDA, promoted tumor cytoplasmic Cxcl9/Cxcl10, indicating that immunotherapy alters the subcellular localization of Cxcr3 ligands in tumor cells." (PMID 36472588, 2023). "Interestingly, we also found that the abnormal expression of CXCL9, CXCL11, and CXCL13 is significantly associated to tumor stage, indicating that these CXCLs are closely related to tumor invasion and metastasis." (PMID 36798787, 2023). "Similarly, high expression of CXCL9 and αPD-L1 proteins were detected only in the tumor tissues of mice bearing colorectal (CT26), pancreatic (Panc02) and breast (4T1) tumors after NPSur-C9AP treatment." (PMID 37031188, 2023). "Based on subgroup marker genes, the cell cluster highly expressing LGMN was annotated as M2 cells, the cell cluster with high expression of CXCL9 was annotated as M1 cells, and the cell cluster highly expressing FABP4 was annotated as non-tumor-associated macrophages (NTAMs)." (PMID 36969247, 2023). "As a result, STING agonist administration enhances the expression of IFN-β and other proinflammatory cytokines (e.g., IL-6 and TNF-α) or chemokines (e.g., CCL2/3/4/5 and CXCL9/10), the maturation and functions of DCs, and the expansion of tumor-infiltrating CD8+ T cells." (PMID 38008741, 2023). "The deletion of PTPN2 in T cells not only promoted the activation and cytotoxic potential of tumor-infiltrating/resident T cells (as reflected by IFNγ, TNF and GZMB levels), but also enhanced STAT-1 signaling in AT3-OVA tumor cells, the expression of Cxcl9 and the recruitment of T cells." (PMID 37500611, 2023). "The increased abundance of IFNγ secreting CD4+ TILs in CaMKK2-deficient mice, in addition to chemotactic signals from DC-like TAMs (Cxcl9, Cxcl10), may explain the enhanced tumor penetrance seen by CD4+ and myeloid cells in the setting of CaMKK2 deficiency." (PMID 36309495, 2022). "Under the chemotactic effect of CXCL9, CXCL10, and CXCL11, activated Th1 cells reach the tumor site to exert phagocytosis and upregulate CXCL9, CXCL10, and CXCL11 secretion, thus recruiting more T lymphocytes to participate in the immune response at the lesion site." (PMID 36479091, 2022). "Therefore, the tumor suppressive effects of cyclin G2 are mediated through its regulation of CXCL9 secretion from macrophages under the action of IFN-γ." (PMID 36566226, 2022). "Notably, also enhancing the recruitment of CTL cells in situ (e.g., inducing CXCL9/10) was effective in inducing the tumor clearance but gave an unfavorable outcome for the cytokine syndrome." (PMID 35350575, 2022). "Similar correlations were shown for CXCL9, which indicated that increased CXCL9 might enhance M1 macrophage infiltration into BCa tumor tissue." (PMID 35359417, 2022). "First, CCL5 produced by cancer cells attracted T cells into the tumor tissue, then T cells activated cancer antigens, then tumor antigens induced CXCL9 to secrete by immune cells dependent on the release of IFN-γ, and finally CXCL9 promotes further tumor infiltration by T cells." (PMID 36618371, 2022). "An in vivo preclinical study showed the inhibition of anti-PD-1 inhibitor effects in CXCR3 knockout mice, indicating that the homing of T cells to the tumor through the CXCL9,10,11/CXCR3 axis may be critical for anti-PD-1 inhibitor efficacy." (PMID 36289760, 2022). "Moreover, IFN-γ enhances the tumoricidal action of M1 macrophages and the recruitment of NK and T cells from the periphery to the tumor site via CXCL9 and CXCL10 chemokines." (PMID 36428727, 2022). "CXCL9 mediates lymphocyte infiltration to focal sites and inhibits tumor growth." (PMID 36479091, 2022). "In addition, mice treated by silencing CXCL9 with short hairpin RNA got greater tumor burden by disrupting natural killer cell recruitment into tumors." (PMID 35392957, 2022).
tumor (continued). "Indeed, cDC1 expression of the XCR1 chemokine receptor, CXCL9 and IL-12 is indispensable for breast cancer tumor rejection." (PMID 36230990, 2022). "In addition, CXCL9 mRNA expression was increased by RXC004 within the tumor microenvironment of this model." (PMID 36922934, 2022). "In addition, the expression of CXCL9/10/11/13 in primary tumor samples was remarkably higher than normal samples, whereas CXCL2/3/4/6/7/8/12/17 transcription levels were significantly lower (all P < 0.05)." (PMID 35725915, 2022). "Conversely, the overexpression in CCA tumor cells of CXCL9, a ligand of C-X-C motif chemokine receptor (CXCR) 3, induces the recruitment of NK cells that infiltrate the tumor and positively correlated with postoperative overall survival in a cohort of 70 patients." (PMID 39301518, 2022). "Interestingly, we found the highest number of CXCL9-overexpressing tumours in the clear-cell subtype, which is the subtype that responded best in the ICB monotherapy trials so far." (PMID 35314795, 2022). "In addition, we also observed in our in vitro study that a STAT3 inhibitor increased CXCL9 expression in tumor cells, indicating the balance of p-STAT1/p-STAT3 was a determinant in regulating chemokine production in tumor cells." (PMID 35925680, 2022). "Ginseng-derived nanoparticles can reprogram tumor-associated macrophages in colon cancer to increase CCL5 and CXCL9 secretion and recruitment of CD8+ T cells into the tumor bed; these nanoparticles synergized with PD-1 mAb therapy with no detected systemic toxicity." (PMID 36386161, 2022). "Genome-wide studies showed that EZH2 levels are negatively correlated with CD8+ T cells, mainly inhibiting the production of tumor TH1-type chemokines CXCL9 and CXCL10 and thus reducing the recruitment of T cells, while the binding of carboxyl structure of ARID1A to EZH2 can reverse this step." (PMID 36713412, 2022). "Immune cells can also directly influence the phenotype and function of tumor vessels through various cytokines, such as cytokines that inhibit tumor angiogenesis (interferon-α, interleukin-12, interleukin-18 or tumor necrosis factor) and chemokines (CXCL9, CXCL10 or CCL21)." (PMID 36569915, 2022). "Proteins associated with tumor regression including granzyme A (GZMA) and Th1 markers such as the C-X-C motif chemokine ligand family (CXCL9, CXCL10, CXCL11) and interferon gamma (IFNG) mirrored the checkpoint inhibitor decreases seen in tissue during single agent pembrolizumab therapy." (PMID 36572780, 2022). "Moreover, tumor-infiltrating DCs, especially CD103+ DCs, boost the infiltration of effector T cells into the tumor by producing CXCL9/10 and hence recruiting CXCR3+ T cells." (PMID 33603130, 2022). "In addition, our preclinical findings above strongly suggest that those tumours with high CXCL9 expression display an increased response to immune checkpoint blockade." (PMID 35314795, 2022). "Notably, it has been reported that CXCL-9 expression in the tumor microenvironment at the pre-treatment stage affects the local immune landscape in patients treated with CAR-T cell therapy." (PMID 36726971, 2022). "Studies showed that CXCL9 and CXCL10 may cause functional NK cell deficiencies and lead to deterioration of the tumor microenvironment of cHL." (PMID 35452413, 2022). "While we did observe only a slight, non-significant increase in Cxcl9 ascites concentration upon Brca2 loss, Cxcl10 was more than fivefold higher than in Brca2WT tumours." (PMID 35314795, 2022). "In this study, we demonstrate that CXCL9 is not only a surrogate for an enhanced, interferon-driven immune response, but that its overexpression improves immune infiltration, thereby inhibiting tumour growth." (PMID 35314795, 2022). "This is consistent with the possibility that cells other than T cells might upregulate the expression of HRL, particularly VCAM-1 and CXCL9, on early-stage tumor endothelial cells." (PMID 36531040, 2022).
tumor (continued). "Furthermore, blocking CXCL9 in mice canceled the tumor growth inhibition initially obtained with avelumab." (PMID 36429101, 2022). "However, a high ratio of CD8+ T cells within the tumor areas in relation to the total T cells in the stroma was correlated with the secretion of CXCR3 ligands (CXCL9, CXCL10 and CXCL11) and the CCR5 ligand CCL8." (PMID 35954489, 2022). "VCAM-1, ICAM-1, and CXCL9 are key HRL for infiltration of CD8+ T cells in several tumor models." (PMID 36531040, 2022). "First, it may be attributed to the trafficking of the antigen specific CD8 +T cells to the location of the tumor (as implied by the study with CXCL9 and CXCL10)." (PMID 35459734, 2022). "They propose that Dipeptidyl peptidase (DPP4) inhibition increases tumor content of CXCL9/10, which recruits CXCR3 + NK and T cells, and DPP8/9 inhibition activates the inflammasome, resulting in proinflammatory cytokine release and Th1 response, further enhancing the CXCL9/10-­CXCR3 axis." (PMID 36479091, 2022). "In a mouse tumor model, CXCL9/10 recruited and activated CD8+ T cells." (PMID 35806328, 2022). "Furthermore, oncolytic viruses can function as strong inducers of CXCL9 and 10 in the tumor microenvironment." (PMID 35626062, 2022). "We found that when neutrophils were co-cultured with cisplatin-pretreated tumor cells, they expressed significantly higher levels of chemokines, such as CXCL9, CXCL10, and CXCL11, which could be key regulators of recruitment of T cells into tumor tissues." (PMID 35784745, 2022). "Similarly, the CXCL9/10/11 overexpression in Lewis Lung carcinoma cells increases the CD8 T-cell recruitment and controls the tumor growth alone or in association with an anti-PD-1 Ab." (PMID 36429101, 2022). "However, when we took into account the relative localization of T cells within the tumor, we also found a positive correlation between CXCL9, CXCL10 and a high CD8+ T cell ratio within and close to tumor nests." (PMID 35954489, 2022). "Mice experiment showed that CXCL9 could enhance NK cell recruitment into tumors to conduct anti–tumor immunity." (PMID 35392957, 2022). "Speculatively, CXCL-9 circulating levels may provide information about the role of the tumor microenvironment in the onset of ICANS." (PMID 36726971, 2022). "Several factors could affect apparent number of CD4+ T cells in tumor: recruitment (CXCL9/10), proliferation (IL‐15), and death (IL‐2)." (PMID 34898004, 2022). "Regarding the tumors, it has been well studied that CXCL9/10/11 (ligands for CXCR3) produced by macrophages and DCs, along with CCL5 (ligands for CCR5) secreted by tumor cells, are associated with T cell recruitment to the TME and a favorable response to chemotherapy and immunotherapy." (PMID 35925680, 2022). "Furthermore, the chemokines CXCL9 and CXCL10 that are greatly implicated in the recruitment of CD8+ T cells to tumor were also upregulated after the treatment with anti-PD-1 antibody, and were further increased in response to the combined treatment." (PMID 35738798, 2022). "While the proportion of the TILs did not significantly differ between the cytokine highly and lowly expressing tumors, CXCL10 (IP-10) and CXCL9 (MIG), known to belong to the CXC chemokine subfamily were associated with increased lymphocyte quantities in the tumor samples." (PMID 35927313, 2022). "Since PC7A could activate the STING-type I IFN pathway, we examined whether STING activation is required for PC7A to induce CXCL9 in tumor." (PMID 35623658, 2022). "One hypothesis that warrants further study is that an increased chemotaxis of activated and tumor antigen-specific cytotoxic T-cells to the tumor, potentially via chemokines such as CXCL9 and CXCL10." (PMID 36532027, 2022).
tumor (continued). "Cxcl9 was about threefold higher expressed in ascites in Cxcl9+ tumour-bearing mice than in the control group (median 4.58 vs. 1.45 pg/mg total protein; P = 0.003), whereas there was no significant change in Cxcl10 (median 6.62 vs. 6.07 pg/mg total protein; P = 0.90)." (PMID 35314795, 2022). "Besides these scores, the XP genes, immune-specific single genes (CD8A, CXCL9, CD274, and CXCL13) and tumor mutational burden (TMB) were cross-correlated." (PMID 35174087, 2022). "However, a limitation of our experimental approach is that we neglect other immune cell cytokine influences that normally affect CXCL9 expression in tumour cells." (PMID 35314795, 2022). "It is worth of note that CXCL9 tissue expression was associated with CD8+ T lymphocyte infiltration in different solid tumors, underlining the importance of such a chemokine for an effective anti-tumor immune response." (PMID 35361879, 2022). "Moreover, there was a moderate correlation between Cxcl9 ascites concentration and the number of tumour-infiltrating T cells." (PMID 35314795, 2022). "In anti-PD-1-treated mice, CXCR3 and its ligands are essential in generating CD8+ T lymphocyte responses, and the production of CXCL9 promotes anti-PD-1-induced anti-tumor responses, suggesting that CXCR3 facilitates the interaction between DCs and T lymphocytes in the TME." (PMID 36479091, 2022). "In the HGSOC subtype, the proportion of CXCL9-high tumours is rather low." (PMID 35314795, 2022). "CXCL9 could contribute to the inhibition of angiogenesis and tumor progression by recruitment of T lymphocytes." (PMID 35677536, 2022). "Accordingly, these data provide strong evidence that B3GALT4 overexpression may promote CD8+ T lymphocyte recruitment into tumor sites via CXCL9 and CXCL10 in NB." (PMID 36284313, 2022). "We investigated whether upregulation of stromal Cxcl9/10 also played a necessary role in the Foxf2-mediated tumor suppression." (PMID 36369237, 2022). "Interestingly, a very recent study found that “exhausted” T cells in the tumor microenvironment that were actively recruited via CXCL9 and CXCL10 can also be considered chemokine-producing cells." (PMID 35626062, 2022). "CXCL9 also acts on vascular endothelial cells to inhibit tumor angiogenesis." (PMID 36566226, 2022). "Lung tumors were isolated and CXCL9 in the supernatant of homogenized tumor cells was measured." (PMID 35389889, 2022). "In addition, increased expression of CD8α, CXCL9, CXCL10, Granzyme A (GZMA), Granzyme B (GZMB), and IFN-γ was observed in Six1-deficient tumor tissues." (PMID 34782761, 2021). "Using the same ovarian cancer model, Zou and colleagues showed that Ezh2 deficiency in T cells suppressed control of tumor progression, while combined Ezh2 and DNMT inhibitors improved the efficacy of anti-PD-1 therapy by increasing the production of CXCL9 and CXCL10." (PMID 33403469, 2021). "The traditional concept is that CXCL10/CXCL9 largely produced at the tumor site is associated with directing the migration of CXCR3+ effector CD4+ and mostly effector -cytotoxic CD8+ T cells, and CXCR3+ NK cells to the tumor site." (PMID 34944943, 2021). "Furthermore, CXCL9/MIG expression was corelated with the presence of tumor-infiltrating lymphocytes as well as post-operative survival." (PMID 34611474, 2021). "Additionally, two-way ANOVA demonstrates a significant effect of the tumor on the renal gene expression of Cxcl1, Cxcl9, and Cxcl10." (PMID 34445729, 2021). "At this point, we do not exclude the possibility that following peripheral administration some of the injected CXCL10-Ig or CXCL9-Ig would enter the tumor site, and therefore may have an additional contribution to CXCR3+ cell recruitment to the TEM." (PMID 34944943, 2021). "Moreover, we observed that EMP3 affected macrophages, causing inhibition of antitumour immunity via suppression of CD4+ and CD8+ T cell infiltration into GBM tumours and downregulation of CXCL9 and CXCL10 production by macrophages." (PMID 33964937, 2021).
tumor (continued). "Future studies will address whether CXCR3 expression on tumor cells results in a more tumorigenic TME in the context of CXCL9 or CXCL10 secretion." (PMID 34433873, 2021). "Our laboratory further demonstrated that hedgehog signaling in hepatocellular carcinoma promotes the immunosuppressive M2 phenotype of TAMs, which further impedes CD8+ cytotoxic T lymphocyte trafficking into the tumor stroma via suppression of CXCL9 and CXCL10." (PMID 34771482, 2021). "There are also studies that combine IL-2 and CXCL9 to slow angiogenesis and tumor progression." (PMID 33854600, 2021). "STRING analysis of leading-edge genes in these macrophage activation signatures, showed that fatty acid stimulation genes upregulated in MAC-MT in tumor were dominated by metallothionine genes, while inflammatory stimulation genes included several chemokines (CXCL9, CXCL10)." (PMID 34936871, 2021). "Moreover, the strong expression of CXCL9 and CXCL10 within tumour tissues is also associated with high CD8+ T cell infiltration in melanoma patients." (PMID 33809369, 2021). "In addition, activation of intra-tumoral Batf3-DCs was required for optimal trafficking of CD8 T cells into the core of the tumor, a process mediated by CXCL9 secretion." (PMID 34276686, 2021). "CXCL9 mediates local lymphocyte infiltration into tumor tissue, which suppresses tumor growth." (PMID 34206510, 2021). "For example, effector immune cells, such as CD8 + Teff cells, IFN-γ-expressing T helper 1 (TH1) cells and natural killer (NK) cells, can be attracted to the tumor microenvironment by CXC-chemokine ligand 9 (CXCL9), CXCL10 and CXCL11, and exert potent antitumor effects." (PMID 34579759, 2021). "CXCL9 stimulates lymphocytes to enter tumors and enhances anti-tumor immune monitoring." (PMID 33854600, 2021). "CXCL5 and CXCL9 chemokines are essential determinants of tumor development and malignancy." (PMID 33925575, 2021). "Furthermore, EMP3 suppressed T cell infiltration into GBM tumours by inhibiting the secretion of CXCL9 and CXCL10 by macrophages and led to an effective response to anti-PD1 therapy." (PMID 33964937, 2021). "Moreover, IL-12 facilitates antigen presentation by upregulating MHCI on tumor cells, favoring polarization to M1 macrophages and attracting effector immune cells by enhancing the production of the chemokines CXCL9, CXCL10 and CXCL11." (PMID 33418929, 2021). "CXCL9 also reduced tumor size and attenuated angiogenesis in the LLC model." (PMID 34503058, 2021). "Likewise, CXCL9 has been suggested to promote tumor progression by inducing STAT3-dependent suppression of cytotoxic T cells." (PMID 34203869, 2021). "CXCL9+M2, the subtype also enriched in tumor tissues, showed an opposite enrichment pattern." (PMID 34659209, 2021). "Therefore, the analysis consisting of tumour purity adjustment between CXCL9 expression and immune-related biomarker expression in BC tissues was completed using the TIMER database." (PMID 34527583, 2021). "Therefore, tumor cells with low expression of CXCL9 make insufficient enrichment of TRAIL+NK cell, which leads to tumor cell growth." (PMID 33854600, 2021). "Moreover, the results of the TCGA RNA-seq data analysis using the TIMER and UALCAN databases indicated that CXCL9 mRNA expression was drastically higher in BC than in normal tissues among a wide range of tumour types." (PMID 34527583, 2021). "iNOS dependent anti-tumor TAMs skew the TME towards cytotoxicity through stimulating Th1 responses via secretion of CXCL9 and CXCL10, inducing cytotoxic CD8s through TNFα and IL1β, and direct killing of tumor cells through nitric oxide (NO) and Reactive Oxygen Species (ROS)." (PMID 34222022, 2021). "However, previous reports suggested that anti-cancer drugs also have the potential to induce CXCL9/10/11 release from cancer cells, and promote anti-tumor effects." (PMID 34413454, 2021).